TIMELESS (timeless circadian regulator)
Description:
Plays an important role in the control of DNA replication, maintenance of replication fork stability, maintenance of genome stability throughout normal DNA replication, DNA repair and in the regulation of the circadian clock. Required to stabilize replication forks during DNA replication by forming a complex with TIPIN: this complex regulates DNA replication processes under both normal and stress conditions, stabilizes replication forks and influences both CHEK1 phosphorylation and the intra-S phase checkpoint in response to genotoxic stress. During DNA replication, inhibits the CMG complex ATPase activity and activates DNA polymerases catalytic activities, coupling DNA unwinding and DNA synthesis. TIMELESS promotes TIPIN nuclear localization. Plays a role in maintaining processive DNA replication past genomic guanine-rich DNA sequences that form G-quadruplex (G4) structures, possibly together with DDX11. Involved in cell survival after DNA damage or replication stress by promoting DNA repair. In response to double-strand breaks (DSBs), accumulates at DNA damage sites and promotes homologous recombination repair via its interaction with PARP1. May be specifically required for the ATR-CHEK1 pathway in the replication checkpoint induced by hydroxyurea or ultraviolet light. Involved in the determination of period length and in the DNA damage-dependent phase advancing of the circadian clock. Negatively regulates CLOCK|NPAS2-ARTNL/BMAL1|ARTNL2/BMAL2-induced transactivation of PER1 possibly via translocation of PER1 into the nucleus. May play a role as destabilizer of the PER2-CRY2 complex. May also play an important role in epithelial cell morphogenesis and formation of branching tubules (By similarity).
Synonyms: hTIM; TIM; TIM1; FASPS4
Tractability: Small molecule: a structure with a bound ligand is known. PROTAC: ubiquitination databases record sites on it.
Gene: Protein-coding gene on chromosome 12 (56,416,363 to 56,449,445, reverse strand). Ensembl gene ENSG00000111602.
Subcellular location: Nucleus; Chromosome
Subcellular location (Human Protein Atlas): Nucleoplasm
Pathways (Reactome):
DNA Repair: Processing of DNA double-strand break ends
Gene Ontology:
Molecular function: enzyme activator activity; protein binding; DNA binding; identical protein binding
Biological process: cell cycle phase transition; cellular response to bleomycin; cellular response to cisplatin; cellular response to hydroxyurea; DNA damage response; mitotic intra-S DNA damage checkpoint signaling; negative regulation of DNA-templated transcription; positive regulation of double-strand break repair; positive regulation of double-strand break repair via homologous recombination; regulation of cell population proliferation; regulation of circadian rhythm; replication fork processing; circadian rhythm; detection of abiotic stimulus; DNA repair; DNA replication checkpoint signaling; morphogenesis of an epithelium; replication fork arrest
Cellular component: chromatin; chromosome; nucleoplasm; nucleus; replication fork protection complex; site of double-strand break; nuclear replication fork
Genetic constraint (gnomAD): Loss-of-function variants: 124 observed, 168.01 expected, observed/expected ratio (o/e) 0.74, 90% interval 0.64 to 0.86. The upper end of that interval is the gene's LOEUF score, 0.86, which puts it in group 3 of 6, group 1 being the genes least tolerant of losing a copy. Missense variants: 1,389 observed, 1,523.4 expected, observed/expected ratio (o/e) 0.91, 90% interval 0.87 to 0.95. Synonymous variants: 554 observed, 582.02 expected, observed/expected ratio (o/e) 0.95, 90% interval 0.89 to 1.02.
Homologues: Orthologues: chimpanzee TIMELESS (99% identical), macaque TIMELESS (96% identical), pig TIMELESS (90% identical), rabbit TIMELESS (89% identical), guinea pig TIMELESS (86% identical), mouse Timeless (84% identical), rat Timeless (82% identical), tropical clawed frog timeless (67% identical), zebrafish timeless (61% identical), Drosophila melanogaster timeout (35% identical), Caenorhabditis elegans tim-1 (28% identical).
Diseases named in the same sentence as TIMELESS in open-access papers:
TIMELESS is named in the same sentence as 47 diseases in open-access papers, as found by Europe PMC text mining. Sharing a sentence is not in itself a finding about the gene and the disease. The quoted sentences say what the papers report.
breast carcinoma (23 papers, 2009 to 2025). "Specifically, high expression of TIMELESS has been observed in human breast cancer tissues, with two associated SNPs (rs2291738 and rs7302060) linked to an increased risk of breast cancer." (PMID 38178094, 2024). "Overexpression of TIMELESS was substantially linked to a worse prognosis and a more advanced tumor stage in breast cancer." (PMID 38053143, 2023). "The expression levels of rhythm genes, such as CLOCK, PER1, PER2, PER3, CRY2, RORC and TIMELESS, are associated with the metastasis-free survival of breast cancer patients." (PMID 35180863, 2022). "Among genetic association studies on circadian genes and their impact on cancer development, only one publication has demonstrated a significant relationship between polymorphic variants of TIMELESS (rs7302060, rs2291738) and breast cancer risk." (PMID 31739444, 2019). "Elevated expression of TIMELESS was significantly associated with more advanced tumor stage and poorer breast cancer prognosis." (PMID 24161199, 2013). "Our previous case–control study demonstrated significant genetic and epigenetic associations of TIMELESS and breast cancer risk." (PMID 24161199, 2013). "Specific TIMELESS alleles have been correlated with hormone-sensitive breast cancers; furthermore, hypomethylation of the TIMELESS promoter is implicated in higher-stage breast cancers, and breast cancer has been shown to overexpress TIMELESS relative to normal breast tissue." (PMID 35163264, 2022). "In the current study, we observed that TIMELESS is frequently overexpressed in tumor relative to normal tissues in several cancer types, and that elevated expression of TIMELESS is significantly associated with later tumor stages and poorer breast cancer prognosis." (PMID 24161199, 2013). "The expression profiling analysis of the tissue-specific microarray data suggests that TIMELESS is frequently overexpressed in various types of tumor tissues, and elevated TIMELESS expression is associated with advanced tumor stage and poorer breast cancer prognosis." (PMID 24161199, 2013). "High mRNA levels in breast cancer of the positive regulator TIMELESS has been significantly associated with shorter relapse-free survival and recently been regarded as a promising marker of tamoxifen resistance in women with estrogen receptor alpha-positive breast tumors." (PMID 19662092, 2009). "Polymorphisms in CLOCK, NPAS2, CRY2, RORA, TIMELESS, and ARNTL have been associated with breast cancer." (PMID 40534841, 2025). "IHC testing verified that the TIMELESS expression of the TIMELESS protein was moderately positive in breast cancer, lung cancer, and renal cancer from clinical cancer specimens." (PMID 38053143, 2023). "Abnormal expression of TIMELESS was significantly related to more advanced tumor stage and poorer prognosis of breast cancer, as well as infiltrating immune cells such as cancer-associated fibroblast infiltration in various tumors." (PMID 38053143, 2023). "In fact, the expression of certain specific circadian genes (BMAL1, PER2, and TIMELESS) has been demonstrated to be disrupted in breast cancer cell lines." (PMID 36012374, 2022). "The expression of six rhythm genes, CRY2, NFIL3, PER1, EGR3, NR1D1 and TIMELESS, was significantly changed in breast cancer compared with normal breast tissues." (PMID 35180863, 2022). "TIMELESS promoted breast cancer progression by activating MYC and regulated cancer cell progression via the Sp1/ACER2/S1P axis." (PMID 35715407, 2022). "TIMELESS was also reported to serve as a tumor suppressor and inhibit breast cancer cell invasion and metastasis by knocking down the expression of MMP9." (PMID 35715407, 2022). "The upregulation of TIMELESS has also been found in cervical carcinoma, colorectal cancer, and breast cancer, and the downregulation of RORA has been found in many cancers including hepatocellular carcinoma, gastric cancer, melanoma, and breast cancer." (PMID 35078435, 2022).
breast carcinoma (continued). "TIMELESS plays an important role in the development of breast cancer, mainly in its influence on the proliferation ability of breast cancer cells." (PMID 33430865, 2021). "The overexpression of TIMELESS repressed the invasion and metastasis of breast cancer cells, while down-regulating TIMELESS facilitated the invasion and metastasis of breast cancer cells." (PMID 33430865, 2021). "While silencing TIMELESS, F-actin was organized in abundant stressed fibers, i.e., overexpression of TIMELESS in breast cancer cells inhibited the organization of loose actin into F-actin while TIMELESS knocking down promoted the assembly process of actin." (PMID 33430865, 2021). "Similar results were obtained in the examination of MMP9 protein level in breast cancer cells, that is, the overexpression of TIMELESS increased the expression of endogenous MMP9, while TIMELESS knockdown inhibited the protein level of MMP9." (PMID 33430865, 2021). "TIMELESS (timeless circadian regulator) is one of the core genes involved in the biological rhythm and is abnormally expressed in liver cancer, breast cancer and lung cancer." (PMID 32528520, 2020). "Upregulation of TIMELESS dramatically enhanced, while knockdown of TIMELESS suppressed the self-renewal of cancer stem cells (CSCs), cell invasion and migration abilities of breast cancer cells in vitro." (PMID 29958276, 2018). "On the other hand, CLOCK and TIMELESS were found to be over-expressed in tumor tissue in comparison with normal adjacent breast cancer tissues." (PMID 29958276, 2018). "TIMELESS, a circadian and cell-cycle regulator that may act as a molecular bridge between these two regulatory systems, has been reported to be overexpressed in many breast cancer cells, with the increased expression being linked to increased proliferation and poorer prognostic outcome." (PMID 26097876, 2015). "The key circadian genes, PERIOD 2 (PER2 variant 2), CLOCK, TIMELESS, CRYPTOCHROME 1 (CRY1) and CRYPTOCHROME 2 (CRY2) were all also significantly expressed in all breast cancer cell lines and all patients’ breast cancer tissues examined." (PMID 24683528, 2013). "We also tested one of the potential roles of TIMELESS suggested by our network analysis using a MTS assay and observed that TIMELESS knockdown decreased the proliferation rate of MCF7 breast cancer cells." (PMID 24161199, 2013). "In addition, HPA database demonstrates that TIMELESS protein was moderate to strong positively in breast cancer, colorectal cancer, lung cancer, liver cancer, renal cancer, and thyroid cancer." (PMID 38053143, 2023). "Melatonin also decreases estrogen production, which may occur via the CRY-interacting protein TIMELESS that regulates sphingolipid metabolism-directed breast cancer cell growth." (PMID 35163264, 2022). "On the contrary, knockdown of TIMELESS promoted the invasion and metastasis of breast cancer cells." (PMID 33430865, 2021). "However, there are few reports regarding the mechanisms on TIMELESS regulating the invasive and metastatic ability of breast cancer cells." (PMID 33430865, 2021). "This suggested that TIMELESS might play an important role in the invasion and metastasis of breast cancer cells." (PMID 33430865, 2021). "Our study reveals a new molecular regulatory mechanism, that is, TIMELESS can inhibit breast cancer migration and invasion by reducing the transcription activity of MMP9, and systematically expounds the molecular mechanism of TIMELESS regulating NF-κB/MMP9 pathway." (PMID 33430865, 2021). "Our study showed that overexpression of TIMELESS could significantly inhibit the invasion and metastasis of breast cancer cells ZR-75-30 and the assembly of F-actin protein." (PMID 33430865, 2021). "In this study, a novel molecular mechanism of TIMELESS expression regulating the invasion and metastasis of breast cancer is acquired, which may provide a new basis for the treatment of metastatic breast cancer." (PMID 33430865, 2021).
breast carcinoma (continued). "TIMELESS plays a crucial role in the self-renewal process of breast CSCs and interacts with Sp1/c-jun to induce miR-5188 expression by promoting c-jun-mediated transcription, thus promoting breast cancer progression." (PMID 32528520, 2020). "A general observation from this study is a statistically significant diminished expression level of CRY2, and PERs and an increased expression level of CLOCK and TIMELESS in the breast cancer tissue samples in comparison with the adjacent normal tissue samples." (PMID 29958276, 2018). "In estrogen receptor-positive breast cancer, the most prevalent type of breast cancer, SP1 interacts with the circadian gene TIMELESS (TIM) to increase alkaline ceramidase 2 (ACER2) and enhance mitochondrial respiration." (PMID 36077352, 2022). "We aimed to investigate the biological functions and molecular mechanisms of circadian gene TIMELESS circadian regulator (TIM) in estrogen receptor (ER)-positive breast cancer and provide a new therapeutic target for breast cancer patients." (PMID 33093451, 2020). "Our study results support a putative role of several loci in circadian genes (CLOCK, TIMELESS) and genes of melatonin biosynthesis (MTNR1A) in the development of breast cancer." (PMID 31358835, 2019). "Considerable expression of key circadian genes, PERIOD 2, CLOCK, TIMELESS, CRYPTOCHROME 1, and CRYPTOCHROME 2 was also seen in all breast cancer cell lines and all patients’ breast cancer tissues." (PMID 24683528, 2013). "Similar to TIMELESS, an important component of the circadian clock, these cancers include non-small cell lung cancer, colorectal cancer, nasopharyngeal carcinoma (NPC), gliomas, and breast cancer, all of which display abnormal expression of TIMELESS and exhibit increased tumor aggressiveness." (PMID 38053143, 2023). "In this study, we identified that TIMELESS may repress the invasion and metastasis of breast cancer cells via inhibiting the acetylation of p65, inhibiting the activation of NF-κB, thus down-regulating the expression of MMP9, and then inhibiting the invasion and metastasis of breast cancer cells." (PMID 33430865, 2021).
lung carcinoma (8 papers, 2012 to 2024). "TIMELESS overexpression in lung cancer is associated with low patient survival." (PMID 33430865, 2021). "Consistent with this, other studies have shown a correlation between TIMELESS overexpression and poor prognosis in lung cancer, and TIMELESS has been used to build a predictive model of survival in lung cancer." (PMID 38261568, 2024). "TIMELESS and FGF are known to modulate lung morphogenesis, and their overexpression in lung cancer is associated with a low survival rate." (PMID 36241659, 2022). "TIMELESS was significantly upregulated in lung tissue of clinical lung cancer patients as well as TCGA and Oncomine databases, while RORA was downregulated." (PMID 35078435, 2022). "A first interesting observation about these genes is that many of them have been positively implicated in breast and/or lung cancer progression and resistance to therapy: AURKA, CAV2, RAB27A, RAD51, TIMELESS, TIMM17A." (PMID 22347440, 2012). "However, the regulation and mechanism of action of TIMELESS in lung cancer remains to be elucidated." (PMID 38261568, 2024).
colorectal cancer (5 papers, 2021 to 2023). A primary or metastatic malignant neoplasm that affects the colon or rectum. "Additionally, the timeless circadian regulator (TIMELESS) gene was transcriptionally activated by H3K27ac in colorectal cancer (CRC), and up-regulated TIMELESS promoted the proliferation, invasion, and metastasis of CRC both in vitro and in vivo." (PMID 36497250, 2022).
ovarian carcinoma (5 papers, 2012 to 2026). A malignant neoplasm originating from the surface ovarian epithelium. "TIMELESS knockdown impaired phenotypic changes in ovarian cancer cells caused by MEX3A overexpression." (PMID 35715407, 2022). "TIMELESS protein expression was also found to be highly overexpressed in ovarian cancer using the data from CPTAC (Clinical Proteomic Tumor Analysis Consortium)." (PMID 35715407, 2022). "This study revealed that TIMELESS knockdown inhibited the proliferation, invasion and metastasis of ovarian cancer cells." (PMID 35715407, 2022). "To reveal the mechanism by which MEX3A regulates TIMELESS expression in ovarian cancer, we observed intron 23 retention of TIMELESS mRNA based on Sashimi plot analysis according to the RNA-seq results after MEX3A knockdown." (PMID 35715407, 2022). "In this study, we analyzed RNA-seq data after MEX3A knockdown in ovarian cancer cells and identified the critical downstream target TIMELESS involved in the alternative splicing regulation of MEX3A." (PMID 35715407, 2022). "Correlation analysis between MEX3A and TIMELESS verified that TIMELESS expression was positively correlated with MEX3A expression in ovarian cancer tissues." (PMID 35715407, 2022). "Above all, we identified that TIMELESS contributed to MEX3A’s carcinogenic function in ovarian cancer." (PMID 35715407, 2022). "TIMELESS was reported to be aberrantly expressed and intimately associated with the development and progression of human cancers, and therefore we selected TIMELESS as the key target of MEX3A in ovarian cancer." (PMID 35715407, 2022). "Taken together, the MEX3A/TIMELESS axis promoted the malignant biological behavior of ovarian cancer cells." (PMID 35715407, 2022). "MEX3A facilitated the proliferation and invasion of ovarian cancer cells by regulating alternative splicing of TIMELESS through the NMD pathway." (PMID 35715407, 2022). "In addition, TIMELESS downregulation also suppressed the clone formation ability of ovarian cancer cells." (PMID 35715407, 2022). "Consistent with the results of colony formation assays in vivo, xenograft experiments showed TIMELESS knockdown could partially reverse the effect of MEX3A overexpression on the growth of ovarian cancer cells in vivo." (PMID 35715407, 2022). "Next, we verified the biological function of TIMELESS in ovarian cancer cells." (PMID 35715407, 2022). "Furthermore, qRT-PCR and western blotting were used to evaluate TIMELESS expression after MEX3A knockdown in ovarian cancer cells, and we found that TIMELESS mRNA and protein expression was obviously decreased after MEX3A inhibition." (PMID 35715407, 2022). "Additionally, we found that TIMELESS overexpression with MEX3A knockdown partially restored the proliferation ability of ovarian cancer cells." (PMID 35715407, 2022). "The goal of the current study was to examine single nucleotide polymorphisms (SNPs) in circadian genes BMAL1, CRY2, CSNK1E, NPAS2, PER3, REV1 and TIMELESS and downstream transcription factors KLF10 and SENP3 as predictors of risk of epithelial ovarian cancer (EOC) and histopathologic subtypes." (PMID 26807442, 2015). "Furthermore, correlation analysis between 182 DEGs and MEX3A was applied using TCGA ovarian cancer data to obtain 7 DEGs (CSNKE1, OBSL1, DNASE1, ZNF711, TIMELESS, SAMD11, and BCL9) that were positively associated with MEX3A expression (Spearman’s correlation≥0.3)." (PMID 35715407, 2022). "In addition, we studied the expression of different TIMELESS transcripts in ovarian cancer in the TCGA cohort, and we found that TIMELESS-201 and TIMELESS-203 expression was higher than TIMELESS-205 and that TIMELESS-201 expression was the highest in ovarian cancer tissues." (PMID 35715407, 2022). "We identified TIMELESS as an important target involved in MEX3A in mediating the growth and metastasis of ovarian cancer cells." (PMID 35715407, 2022).